DDX31 (DEAD-box helicase 31)
Description:
May have DNA helicase activity and RNA helicase activity. Probably have ssDNA and RNA dependent ATPase activity (By similarity).
Synonyms: FLJ13633; FLJ23349; FLJ14578; PPP1R25
Tractability: PROTAC: ubiquitination databases record sites on it; its protein half-life has been measured.
Gene: Protein-coding gene on chromosome 9 (132,592,787 to 132,670,401, reverse strand). Ensembl gene ENSG00000125485.
Subcellular location: Nucleus, nucleolus
Subcellular location (Human Protein Atlas): Nucleoli; Golgi apparatus; Vesicles
Gene Ontology:
Molecular function: protein binding; RNA binding; ATP hydrolysis activity; ATP binding; nucleic acid binding; RNA helicase activity
Biological process: ribosome biogenesis
Cellular component: nucleolus; nucleus
Genetic constraint (gnomAD): Loss-of-function variants: 68 observed, 92.22 expected, observed/expected ratio (o/e) 0.74, 90% interval 0.61 to 0.9. The upper end of that interval is the gene's LOEUF score, 0.9, which puts it in group 3 of 6, group 1 being the genes least tolerant of losing a copy. Missense variants: 880 observed, 935.2 expected, observed/expected ratio (o/e) 0.94, 90% interval 0.89 to 1. Synonymous variants: 355 observed, 356.76 expected, observed/expected ratio (o/e) 1, 90% interval 0.91 to 1.09.
Homologues: Orthologues: chimpanzee DDX31 (99% identical), macaque DDX31 (95% identical), dog DDX31 (80% identical), guinea pig DDX31 (78% identical), rabbit DDX31 (77% identical), pig DDX31 (75% identical), rat Ddx31 (74% identical), mouse Ddx31 (73% identical), tropical clawed frog ddx31 (56% identical), zebrafish ddx31 (53% identical), Drosophila melanogaster CG8611 (37% identical). Paralogues in human: DDX18 (29% identical), DDX10 (26% identical), DDX21 (21% identical), DDX42 (20% identical), DDX43 (20% identical), DDX27 (19% identical), DDX46 (19% identical), DDX24 (19% identical), DDX51 (19% identical), DDX55 (19% identical), DDX50 (19% identical), DDX17 (19% identical), and 26 more.
Diseases named in the same sentence as DDX31 in open-access papers:
DDX31 is named in the same sentence as 12 diseases in open-access papers, as found by Europe PMC text mining. Sharing a sentence is not in itself a finding about the gene and the disease. The quoted sentences say what the papers report.
medulloblastoma (3 papers, 2016 to 2022). A malignant, invasive embryonal neoplasm arising from the cerebellum. "In 2014, Bish and Vogel (2014) found that DDX31 is involved in the growth and maintenance of medulloblastoma." (PMID 35237592, 2022). "Complex rearrangement and focal deletions of the DDX31 gene have also been observed in several Group 4 medulloblastomas; these deletions occur concurrently with amplification of the OTX2 locus, a known medulloblastoma oncogene." (PMID 34795224, 2021). "Recently, the BARHL1/DDX31 super-enhancer was identified as an element that activates the GFI1B oncogene when fused to it by chromosomal deletion in subsets of Group 3 and Group 4 medulloblastomas." (PMID 27310018, 2016).
bladder cancer (2 papers, 2021 to 2023).
renal cell carcinoma (2 papers, 2016 to 2022).
Azoospermia (1 paper, 2022). Absence of any measurable level of sperm,whereby spermatozoa cannot be observed even after centrifugation of the semen pellet. "The ratio of infertility genes expression: DDX5, TNP2, DDX3Y, TDRD6, SOHL2, DDX31, and SYCP3 in infertility cell (azoospermia) in comparison to a normal cell." (PMID 36241908, 2022).
glioma (1 paper, 2022). A benign or malignant brain and spinal cord tumor that arises from glial cells (astrocytes, oligodendrocytes, ependymal cells). "As the co-IP results indicated, GBP2 could interact with KIF22 in glioma cells, but not DDX31 and YTHDF2." (PMID 35436989, 2022).
Infertility (1 paper, 2022). "STRING and Cytoscape analyses presented seven genes, i.e., DDX5, TNP2, DDX3Y, TDRD6, SOHL2, DDX31, and SYCP3, as the hub genes involved in infertility with VASA co-function and protein–protein interaction." (PMID 36241908, 2022).
kidney cancer (1 paper, 2021). Primary or metastatic malignant neoplasm involving the kidney.
pancreatic cancer (1 paper, 2022). "We still found in the analysis results that a small number of patients with high expression of DDX31 had HR less than 1 (DDX31′s HR value partially crossed 1), but the analysis results of most patients showed that it might be a risk factor of pancreatic cancer patients." (PMID 35237592, 2022). "With respect to DDX31's HR value partially crossed 1, we found in the analysis results that a small number of patients with high expression of DDX31 had HR less than 1, but the analysis results of most patients showed that it might be a gene that promotes the risk of pancreatic cancer." (PMID 35237592, 2022). "Moreover, we found that overexpression of DDX31 in normal pancreatic cell lines (HPDE6c7) also significantly enhanced cell proliferation and migration, suggesting that DDX31 can indeed promote the development of pancreatic cancer." (PMID 35237592, 2022). "DDX31 was absent in 25% of pancreatic cancer patients, and its expression in some cancer tissues was similar to that in paracancerous tissues." (PMID 35237592, 2022).
Stroke (1 paper, 2022). Sudden impairment of blood flow to a part of the brain due to occlusion or rupture of an artery to the brain. "Four of these variants (TPTE rs143510517, MEP1A rs62619974, DDX31 rs142792732, and PATL1 rs79336999) were associated with stroke at p < 1 × 10−10." (PMID 36672803, 2022).
tumor (1 paper, 2022). "These evidences indicate that DDX31 can help drive tumor progression and metastasis, and it also proves the rationality of our screening results." (PMID 35237592, 2022). "The 86 tumor tissues were divided into two groups according to the expression of DDX31 (DDX31-Low and DDX31-High)." (PMID 35237592, 2022). "According to the results of IHC, 62.8% (54/86) of patients, the expression of DDX31 was higher in tumor tissues than in paired normal tissues." (PMID 35237592, 2022). "The results revealed that DDX31 overexpression significantly promoted tumor growth." (PMID 35237592, 2022). "We found that the expression of DDX31 was increased in tumor tissues." (PMID 35237592, 2022). "Interestingly, in this series of 86 patients, 16.7% (9/86) of patients, the expression of DDX31 was lower in tumor tissues than in paired normal tissues and the expression was the approximate level in normal and tumor tissues in 26.7% of (23/86) these patients." (PMID 35237592, 2022). "To investigate the expression of DDX31 in PDAC specimens, we performed IHC analysis in 86 tumor tissues and paired normal pancreas tissues." (PMID 35237592, 2022). "In our study, we found that DDX31 promotes the phosphorylation of ERK1/2 and MERK1/2, which may lead to increased tumor proliferation and invasion." (PMID 35237592, 2022).
DDX31 also shares sentences with these, for which no sentence is quoted: breast carcinoma (1 paper); cancer (1).